GNAO1 (G protein subunit alpha o1)
Diseases named in the same sentence as GNAO1 in open-access papers (continued):
Sharing a sentence is not in itself a finding about the gene and the disease.
developmental delay (29 papers, 2017 to 2026). "De novo mutations in GNAO1, the gene encoding the major neuronal G protein Gαo, cause a spectrum of pediatric encephalopathies with seizures, motor dysfunction, and developmental delay." (PMID 37887313, 2023). "Dominant GNAO1 mutations cause an emerging group of childhood-onset neurological disorders characterized by developmental delay, intellectual disability, movement disorders, drug-resistant seizures and neurological deterioration." (PMID 34622282, 2022). "One example of this mechanism was a novel heterozygous variant, GNAO1 NM_020988.2:c.980C > A, p.(Thr327Lys), identified in a child referred for exome sequencing with global developmental delay, central axial hypotonia and hypermobility." (PMID 35869530, 2022). "Developmental milestones are also delayed in most patients with GNAO1 variants and the degree of developmental delay varies from neonatal hypotonia to intellectual disability." (PMID 33298085, 2020). "De novo mutations in GNAO1 were initially associated with Ohtahara syndrome, a severe type of early epileptic encephalopathy characterized by neonatal tonic spasms, severe motor developmental delay, and ID with a suppression-burst pattern on EEG." (PMID 29086067, 2017). "While developmental delay and severe ID are features consistently associated with GNAO1 mutations, epilepsy is variably present and often follows the onset of movement disorders of months or years [64•]." (PMID 29086067, 2017). "GNAO1-associated disorders are ultra-rare autosomal dominant conditions, which can manifest, depending on the exact pathogenic variant in GNAO1, as a spectrum of neurological phenotypes, including epileptic encephalopathy, developmental delay with movement disorders, or late-onset dystonia." (PMID 39897576, 2025). "By utilizing C. elegans, researchers can gain deeper insights into the mechanisms underlying GNAO1 encephalopathy and develop targeted treatments that address the complex interplay of motor dysfunctions, seizures, and developmental delays characteristic of this disorder." (PMID 40771566, 2025). "Notably, most individuals with GNAO1-linked movement disorders also suffer from significant developmental delays." (PMID 40771566, 2025). "A few patients with chromosome 16q deletions encompassing GNAO1 have been described, all harboring significantly larger deletions compared to our case and showing variable associations of dysmorphisms, microcephaly, seizures, and developmental delay." (PMID 35722775, 2022). "More than 30 point mutations in GNAO1 have been described to underline different manifestations of pediatric encephalopathy: epileptic seizures, motor dysfunctions, or the combination of both, accompanied by a developmental delay." (PMID 34685729, 2021). "GNAO1 variants could cause multiple neurodevelopmental phenotypes, including epileptic encephalopathy, involuntary movements, and developmental delay." (PMID 34122306, 2021). "In a further similarity to Gαo, de novo point mutations in GNAI1, some of them—in the same positions as those found in GNAO1 mutant patients, have recently been described to cause dominant infantile neurological disorders with variable degrees of developmental delay, seizures, and hypotonia." (PMID 34685729, 2021). "However, if we noticed unexplained early onset dystonia or chorea as well as severe developmental delay, GNAO1 might be initially considered as a genetic cause." (PMID 33298085, 2020). "The four cases presented in this study illustrate the severe end of the phenotypic spectrum of GNAO1-RD, characterized by profound motor impairment and global developmental delay and all died at a young age." (PMID 41153036, 2025). "GNAO1-related encephalopathy is a rare condition with a broad phenotypic spectrum characterized by cognitive delay, motor and communicative difficulties, epileptic disorder and movement disorders (MDs)." (PMID 36980817, 2023).
developmental delay (continued). "Global developmental delay and subsequent moderate to severe intellectual disability are observed in almost all patients with GNB1, GNAO1, PDE2A, and HPCA variants." (PMID 36003298, 2022). "The phenotypic spectrum of GNAO1-related neurodevelopmental disorders ranges broadly from epileptic encephalopathy, movement disorders, and developmental delay, to the combination of various phenotypes." (PMID 34122306, 2021). "Our theory was supported by sporadic publications describing a milder phenotype in patients with GNAO1 deletion (whole-gene deletion or nonsense variants), including slowly progressive or late-onset dystonic features, with no developmental delays." (PMID 39897576, 2025). "The prevailing characteristics among patients harboring GNAO1 mutations are hypotonia and developmental delay, irrespective of their clinical presentation or biochemical traits." (PMID 40771566, 2025).
Dystonia (28 papers, 2017 to 2026). An abnormally increased muscular tone that causes fixed abnormal postures. "In recent years, GNAO1 mutations have also been associated with milder conditions, including autism and intellectual disability, parkinsonism, and dystonia." (PMID 41460161, 2026). "GNAO1 mutations are also associated with milder phenotypes such as adolescent/adult-onset dystonia, parkinsonism, and ASD, pointing to a wider phenotypic spectrum in GNAO1-related disorders." (PMID 41387899, 2025). "Pathogenic variants in GNAO1-gene are increasingly recognized as a cause of early-onset hyperkinetic movement disorders, including chorea, ballism and dystonia." (PMID 40584247, 2025). "And Gαo mutants carrying a near-normal Ric8 association define the third category (L) that contains partial LOF GNAO1 mutations leading to mild phenotypes such as late-onset dystonia and Parkinsonism." (PMID 40745211, 2025). "Dyskinetic crises in GNAO1-RD are commonly associated with dystonia, choreoathetosis, ballismus, or a combination of these movement disorders." (PMID 38903163, 2024). "Literature data show that both subthalamic and pallidal deep brain stimulation can be effective in GNAO1-associated dystonia and that implantation should be promptly considered in patients with sustained refractory GNAO1-associated dystonia." (PMID 36980817, 2023). "Heterozygous mutations in GNAO1, which encodes the Gαo subunit of heterotrimeric G proteins, cause a spectrum of neurodevelopmental disorders ranging from early‐onset epileptic encephalopathy to dystonia." (PMID 41460161, 2026). "This, together with the emergence of GNAO1 mutations associated with a milder dystonia phenotype, suggests that GNAO1-related disorders might represent a continuous phenotypic spectrum, although the genotype-phenotype correlation is still unclear." (PMID 38874642, 2024). "Movement phenotypes were also reported since the first clinical report and have recently become major presenting symptoms: so far, chorea, dystonia, orofacial dyskinesia, and stereotyped hand movements have been reported in patients of different ages, associated with GNAO1." (PMID 33298085, 2020). "When patients with EIEE had combined dystonia, GNAO1 may be suspected as the causative gene." (PMID 34122306, 2021). "The etiology of dystonia within the group of inherited dystonia was classified as follows: DYT-TOR1A (n = 3), DYT-KMT2B (n = 1), DYT-SGCE (n = 1), DYT-PRKRA (n = 1), DYT-ANO3 (n = 1), GNAO1 gene mutations (n = 2)." (PMID 37321142, 2023). "GNAO1 dystonic phenotype (DYT-GNAO1) should be considered as dopa-responsive dystonia in some cases." (PMID 37034444, 2023). "Dystonia distribution was segmental or focal in 7 patients, and clinical course was nonprogressive in 11 patients, while most of the previously reported patients with GNAO1‐related movement disorders had generalized and rapidly progressive dystonia." (PMID 35722775, 2022). "We highlighted a mild GNAO1‐related phenotype, including adolescent‐onset dystonia, broadening the clinical spectrum of this condition." (PMID 35722775, 2022). "It is crucial to highlight that individuals with GNAO1-RD might encounter dyskinetic crises several years after the onset of dystonia." (PMID 38903163, 2024). "GNAO1-RD exhibits significant clinical heterogeneity, with core symptoms consisting of early-onset epilepsy, developmental delay/intellectual disability, and a hyperkinetic movement disorder, which typically includes chorea, dystonia, and myoclonus." (PMID 38903163, 2024).
Dystonia (continued). "In managing dyskinetic crises in GNAO1-RD, patients should receive comprehensive care following the guidelines outlined in the Dystonia Severity Action Plan (DSAP), which includes criteria for escalation of care level, as needed medications, and appropriate laboratory tests." (PMID 38903163, 2024). "Future identification of autosomal dominant family with GNAO1‐related dystonia and follow‐up of this patient might confirm whether incomplete penetrance is possible in GNAO1‐related disorders." (PMID 35722775, 2022). "GNAO1 mutations should be considered as a cause of adolescent or adult‐onset nonprogressive dystonia, particularly in the presence of a speech involvement even in the absence of seizures or ID." (PMID 35722775, 2022). "There is a limited experience with DBS in patients with GNAO1-related dystonia." (PMID 35725943, 2022). "Three out of 10 patients (with GNAO1, ACTB and KMT2B variants) could be considered for surgical interventions when medical therapies for dystonia fail." (PMID 33446253, 2021). "Additionally, likely pathogenic or pathogenic variants were found in ATP1A3 (n = 5) and GNAO1 (n = 1) for genes causing combined dystonia, as well as ACTB (n = 1), IRF2BPL (n = 1), SPR (n = 1), and TUBB4A (n = 3) for genes linked to dystonia with other neurological or systemic features." (PMID 40533913, 2025). "In a 4-year-old boy (M-020) suffering from intractable dystonia with severe failure to thrive and profound psychomotor retardation, a de novo LPV (c.607G>A;p.Gly203Arg) that was absent from the control databases was identified in the GNAO1 gene." (PMID 33584783, 2020).
Epileptic encephalopathy (27 papers, 2014 to 2026). A condition in which epileptiform abnormalities are believed to contribute to the progressive disturbance in cerebral function. "Recent studies have linked mutations in the gene that encodes for Gαo (GNAO1) to early infantile epileptic encephalopathies/developmental epileptic encephalopathies, diseases whose mechanisms remain to be elucidated at the molecular level." (PMID 40615045, 2025). "Overall, our study offers new insights into the genotype‐phenotype correlation of the GNAO1‐associated epileptic encephalopathy." (PMID 40337144, 2025). "We selected the G203R variant of GNAO1 as a pathogenic allele for testing due to the specific symptom profile of G203R patients, who develop both epileptic encephalopathy and movement disorders." (PMID 41294808, 2025). "GNAO1‐associated disorders have a large spectrum of neurological symptoms, from early‐onset developmental and epileptic encephalopathies (DEE) to late‐onset movement disorders." (PMID 40337144, 2025). "The G203R mutation in the GNAO1 gene arises recurrently de novo and causes epileptic encephalopathy and movement disorder." (PMID 41294808, 2025). "De novo mutations in GNAO1, both gain of function and loss of function, cause neurodevelopmental disorder including developmental and epileptic encephalopathy." (PMID 37248219, 2023). "Most reported patients carrying GNAO1 mutations showed a severe phenotype characterized by early‐onset epileptic encephalopathy and/or chorea." (PMID 35722775, 2022). "Mutations in GNAO1, which encodes the alpha subunit of the G-alpha heterotrimeric G-protein signal-transducing complex, cause early-onset epileptic encephalopathy and severe developmental delay." (PMID 34226506, 2021). "A de novo c.607G>A change in GNAO1 has been previously reported many times in patients with epileptic encephalopathy, suggesting that it is a mutation hotspot." (PMID 33584783, 2020). "An example gene is GNAO1, which is the 23rd most specifically expressed gene in the adult claustrum and is known to cause early onset epileptic encephalopathy." (PMID 31827426, 2019). "Mutations in GNAO1 are associated with epileptic encephalopathy, involuntary movements, and intellectual disability." (PMID 31673306, 2019). "It matches an intronic region of gene GNAO1, a G protein repressor, whose defects are a cause of early-onset epileptic encephalopathy." (PMID 30486775, 2018). "GNAO1 mutations have been associated with two phenotypes: a severe, early‐infantile epileptic encephalopathy with burst‐suppression (EIEE17, OMIM 6154731) and a neurodevelopmental disorder with involuntary movements (NEDIM, OMIM 6174932, 3, 4), with or without seizures." (PMID 35722775, 2022). "Mutations in the GNAO1 gene were first identified in patients with epileptic encephalopathy." (PMID 35725943, 2022). "A genotype-phenotype correlation has recently been suggested in functional in vitro studies, with GNAO1 loss-of-function mutations associated with epileptic encephalopathy and gain-of-function or normally functioning alleles leading to phenotypes dominated by movement disorders [70••]." (PMID 29086067, 2017). "These clinical features place GNAO1-encephalopathy into the bigger group of developmental and epileptic encephalopathies." (PMID 34685729, 2021). "GNAO1 encephalopathy is a rare neurodevelopmental disorder characterized by distinct movement presentations and early onset epileptic encephalopathy." (PMID 33298085, 2020).
Epileptic encephalopathy (continued). "The other one was on gene GNAO1, which was also recently reported to play a significant role in epileptic encephalopathy." (PMID 28155632, 2016). "Of the nineteen genes that we predicted with the highest likelihood to be true Epileptic Encephalopathy genes, two (GNAO1 and GRIN2B) have recently been independently reported and confirmed." (PMID 25014031, 2014). "Our objectives were to expand the current understanding of Gαo-mediated mechanistic pathways and understand how defects in Gαo-effector interactions may contribute to the mechanistic underpinnings of GNAO1 epileptic encephalopathies." (PMID 40615045, 2025). "Furthermore, GNAO1 is closely related to epileptic encephalopathy and neurological dysfunction, PRKCB exerts a regulatory effect on neuronal function, and GRIA2 is closely related to status epilepticus and depression." (PMID 36533076, 2022). "Confirmation that our prioritization approach works came with two recent publications reporting GNAO1 and GRIN2B as a true Epileptic Encephalopathy genes." (PMID 25014031, 2014).